ENSG00000261915 (novel protein)
Gene: Protein-coding gene on chromosome 17 (7,312,661 to 7,319,174, reverse strand). Ensembl gene ENSG00000261915.
Genetic constraint (gnomAD): Missense variants: 365 observed, 434.26 expected, observed/expected ratio (o/e) 0.84, 90% interval 0.77 to 0.92. Synonymous variants: 162 observed, 172.69 expected, observed/expected ratio (o/e) 0.94, 90% interval 0.82 to 1.07.